NF1 (neurofibromin 1)
Diseases named in the same sentence as NF1 in open-access papers (continued):
Sharing a sentence is not in itself a finding about the gene and the disease.
neurofibroma (continued). "The Met992 deletions resulted in a milder phenotype characterized by the quasi-absence of neurofibromas and OPGs but with an increased occurrence of Noonan-like features and pulmonic stenosis, when compared to the “classic” NF1 population." (PMID 34199217, 2021). "Overexpressing EGFR in Nf1 wild-type Schwann cells leads to neurofibroma formation, although to a low penetrance, but not to MPNST." (PMID 34445326, 2021). "After 16 weeks, we assessed complete remission of AD and no progression of NF1, in terms of number and size of neurofibromas, with an overall improvement in the quality of life of the patient (DLQI 0)." (PMID 34275694, 2021). "The hybrid-neurofibroma was found in a NF2 patient, the third ganglioneuroma in a child with NF1." (PMID 32506255, 2020). "Our patient was found to lack the typical signs of NF-1 with absence of Lisch nodules, cafe’-au-lait spots, optic gliomas, multiple other neurofibromas or axillary/inguinal freckling." (PMID 29426349, 2018). "In summary, we demonstrate that ATRX is aberrantly expressed in the majority of NF1-MPNSTs, but not plexiform or atypical neurofibromas." (PMID 29796169, 2018). "Plexiform neurofibromas (PNFs) are noncutaneous neurofibromas which are pathognomonic of NF-1 and overall one of the most challenging neoplasms to manage in NF-1." (PMID 29849532, 2018). "In the GEMM of neurofibromas formation (Nf1 flox/flox; DhhCre), PD-901 reduced tumor volume, but did not result in the induction of apoptosis of tumor cells." (PMID 24681606, 2014). "Neurofibromatosis type 1 (NF1; MIM 162200) is an autosomal dominant disease characterised by café-au-lait spots, axillary/inguinal freckling, iris hamartomas, neurofibromas, optic nerve gliomas, and skeletal abnormalities including sphenoid dysplasia, caused by mutations in the NF1 gene." (PMID 25276129, 2014). "Although previous NF1 clinical studies and case reports, as well as case studies, have included neurofibroma quantification in their methods, the lack of an universal approach for quantification of these tumors is evident." (PMID 25475340, 2014). "Clinicians should be alerted to the presence of MPNSTs when a patient with NF-1 develops unremitting pain not otherwise explained, rapid increase in size of a plexiform neurofibroma, change in consistency from soft to hard, or a neurological deficit." (PMID 25317349, 2014). "In a solitary neurofibroma occurring without stigmata of NF-1, the tumour probably represents the segmental form of NF-1 caused by a later somatic mutation." (PMID 23653673, 2013). "Our group previously characterized a large set of neurofibromas for the presence/absence of AI in the NF1 region by applying microsatellite analysis." (PMID 22916147, 2012). "The characteristics encountered in the present case are identical to those of localized (solitary) neurofibromas not related to NF1." (PMID 20858283, 2010). "Presacral neurofibromas or neurofibromas with presacral involvement are uncommon in patients without NF-1, and have been the subject of sporadic case reports over the past half-century." (PMID 15363097, 2004). "In conclusion, we report here the previously unreported synchronous diagnosis of a presacral neurofibroma and a spitzoid malignant melanoma in a patient without NF-1." (PMID 15363097, 2004). "Pre-sacral neurofibromas are rare in patients without NF-1; likewise, malignant spitzoid melanoma, a controversial histopathological entity, is distinctly uncommon." (PMID 15363097, 2004). "However, as GM-CSFR-βc-/- mutants rescue abnormalities in the setting of a Nf1-/- JMML model, we wondered if we might find a similar rescue in the neurofibroma model." (PMID 40075752, 2025). "Thus, to further validate CRISPRi screen results, we directly tested 2 of the top sgRNAs that were enriched after selumetinib treatment (T10/T0), RASA2 or KEAP1, which were suppressed in NF1-mutant, PRC2-intact neurofibroma cells using 2 independent sgRNA protospacer sequences." (PMID 38216572, 2024).
neurofibroma (continued). "Our study demonstrates that NF1 patients with NF1 exon 24 [19a] skipping typically exhibit a mild phenotype characterized by the absence of severe NF1-specific clinical features, including neurofibromas." (PMID 39001468, 2024). "In sum, these data suggest that Ras pathway and cell cycle regulators regulate selumetinib responses in NF1-mutant, PRC2-intact neurofibroma cells, while tumor suppressor genes and genes affecting cell differentiation may underlie more general growth responses as well as selumetinib responses." (PMID 38216572, 2024). "Similarly, the ERN GENTURIS tumour surveillance guidelines developed for Europe, primarily addressing the clinical assessment and imaging screening of NF1-related tumours in adolescents and adults, provides only a weak recommendation for WBMRI in the monitoring of plexiform neurofibromas." (PMID 38539455, 2024). "Neurofibromatosis 1 (NF1) is a multisystem disorder characterized by café-au-lait spots of the skin, intertriginous freckling, multiple cutaneous neurofibromas, subcutaneous or deep nodular neurofibromas, plexiform neurofibromas, and characteristic ocular signs." (PMID 38655100, 2024). "However, human normal nerve from the same patient (sites where this is no neurofibroma) or healthy donors (normal NF1 status genetically) are typically spared in clinical debulking surgeries." (PMID 37167059, 2023). "An additional small series of patients (n = 7) with NM_000267.3(NF1):c.3112A>G p.Arg1038Gly, have been reported to have CALs and no neurofibroma, but any comparisons of this small group with p.Met992del must be approached with caution due to small patient numbers." (PMID 34897289, 2022). "Likewise, patients with various different NF1 missense pathogenic variants at amino acid residue Arg1809 have multiple CALM with or without freckling and rarely Lisch nodules, but do not exhibit neurofibromas." (PMID 34928431, 2022). "This feature, though not directly related to the decrease in NF1 proteins, may be involved in the collagen accumulation in neurofibroma." (PMID 34011935, 2021). "In addition, one should be cautious to diagnose NF1 if neither CALMs nor neurofibromas are present, because that would be suggestive of mosaic NF1 or another unusual situation." (PMID 34012067, 2021). "Among the intragenic NF1 mutations, the deletion mutation p.Met922del in exon 17 has been correlated with a mild phenotype of typical pigment lesions (CALM or freckling), learning difficulties, and lacking forms of neurofibromas." (PMID 34988040, 2021). "Prevalence of cutaneous and subcutaneous neurofibromas or plexiform neurofibromas in age-dependent subgroups of patients with either type-1 deletions of the NF1 gene, atypical deletions or without large deletions of the NF1 gene (control)." (PMID 33951044, 2021). "However, careful examination of the patient showed no stigmata of NF1 such as dermal or plexiform neurofibromas, optic pathway gliomas, café-au-lait macules, axillary freckling, Lisch nodules, or bony dysplasia and there was no family history of NF1." (PMID 33707600, 2021). "After removal of a neurofibroma, a NF1 needs to be ruled out or established if not known already." (PMID 32506255, 2020). "While in 1-month-old Nf1 mutant nerve neither SCs nor macrophages significantly differed from their normal counterparts, both macrophages and SCs showed significantly altered cytokine gene expression in neurofibromas." (PMID 28256556, 2017). "Mutations in Nf1 and subsequent hyperactivation of downstream signaling pathways of RAS-MEK1/2-ERK1/2 and PI3K-AKT-mTOR are necessary but not sufficient to drive the transformation of neurofibromas to MPNSTs." (PMID 27494873, 2016). "Several studies have tested the hypothesis that NF1 heterozygotes enhance angiogenesis and may promote neurofibroma formation; nevertheless, none of these studies showed so far the role of secreted vesicles in the communication between different cell types." (PMID 25759690, 2015).
neurofibroma (continued). "Moreover, a nullizygous population of cells that is S100β negative is present in human neurofibromas, and NF1+/− multipotent progenitor cells are seemingly recruited to the tumor." (PMID 22550514, 2012). "Similarly, characterization of cells present in neurofibromas by S100β, a marker for the Schwann lineage, has demonstrated that a nullizygous population (NF1−/−) that is negative for S100β expression is present in neurofibromas." (PMID 22550514, 2012). "Although neurofibromas may often occur in the cervicofacial region, intraoral neurofibromas not related to NF-1 are relatively uncommon." (PMID 20858283, 2010). "These abnormalities of suppressor genes, except for NF1, are not present in neurofibromas." (PMID 20205747, 2010). "However, one of the patients from our MNF1 cohort had a positive NF1 analysis on DNA from both affected tissue and blood, though in a mosaic state and two patients had a negative NF1 analysis on DNA from a plexiform neurofibroma and from a CAL spot, respectively." (PMID 33853649, 2021). "Although the initial genotype–phenotype report, demonstrating very mild phenotype in the NF1 p.Met992del-positive individuals, was published a decade ago, the biological reasons why these specific individuals do not develop any externally visible neurofibromas are still unclear." (PMID 30190611, 2019). "More recent work demonstrated that implantation of Nf1−/− SKPs in sciatic nerve tissue, but not subcutaneous implantation in unprimed athymic mice, resulted in neurofibroma formation, further indicating that the microenvironment may be a key regulator of cNF development." (PMID 29695767, 2018). "Ifnb1 was also slightly down-regulated both in 1-month-old Nf1−/− SCs and 1-month-old Nf+/+ macrophages from Nf1fl/fl;DhhCre mice compared to their wild-type controls, suggesting that levels of IFN-β mRNA might be reduced even in early stages of neurofibroma growth." (PMID 28256556, 2017). "The CNS manifestations of NF-1 include FASI, optic pathway gliomas, non-optic pathway intracranial gliomas, dural ectasias and meningoceles, and nerve sheath tumors such as plexiform neurofibromas." (PMID 41185817, 2025). "However, since SKPs are a heterogeneous cell population, the essential questions of which subsets of cells give rise to which subtype of neurofibromas or whether there is a common origin within SKPs to form both cNFs and pNFs in the absence of NF1 remain to be answered." (PMID 36139671, 2022). "Thus, in very young children with suspected NF-1, especially those with a negative family history, the presence of the CARVs observed in this study can be more helpful for diagnosis of NF-1 than other clinical signs with progressive characteristics, such as Lisch nodules or neurofibromas." (PMID 32733046, 2020). "While neurofibromas may be diagnosed in patients with NF2, they are not clearly associated with this syndrome despite the syndrome’s description as a ‘neurofibromatosis’, in contrast to NF1, and many of the reported neurofibromas likely represent misdiagnosed hybrid schwannoma/neurofibromas." (PMID 31161239, 2020). "Very few of the miRNAs identified in the plexiform neurofibroma-MPNST comparison, and none of the selected miRNAs, were detected in the sporadic MPNST – NF1-derived MPNST comparison." (PMID 32076030, 2020). "AURKA was overexpressed and amplified in NF1-related MPNST, but not neurofibromas." (PMID 25026295, 2014). "A study of tumors from the same NF1 patient at the TAGLN locus found that only the MPNST lacked methylation, correlating with increased expression of transgelin, but this is in contrast to another study that found decreased expression relative to neurofibromas." (PMID 32642732, 2020). "A transgenic mouse model has been created, lacking both PTEN and NF1 in Schwann cells and in their precursor, that developed a high-grade peripheral nerve sheath tumor, confirming the importance of PTEN in tumor development and progression from neurofibroma to MPNST." (PMID 31416195, 2019).
melanoma (442 papers, 2004 to 2026). A malignant, usually aggressive tumor composed of atypical, neoplastic melanocytes. "In melanoma, NF1 mutations occur in approximately 12–18% of all cases but are markedly enriched in the desmoplastic melanoma (45–93%)." (PMID 41492362, 2026). "Cutaneous melanoma samples with HRD had significantly higher prevalence of NF1 mutation (36.06% v 18.5%, P < .001) and significantly lower prevalence of V-RAF murine sarcoma viral oncogene homolog B (BRAF) mutation (48.0% v 37.03%, P < .01)." (PMID 41533995, 2026). "The dysregulation of the keratinocyte–melanocyte axis results in the formation of café-au-lait macules and malignant melanoma in NF-1, but the underlying molecular basis of this dysregulation remains elusive." (PMID 41170329, 2025). "Mutations in the BRAF kinase are observed in ∼40–60% of melanoma patients, and other frequent melanoma subtypes involve activating mutations in RAS isoforms (20–30% of patients) or loss of NF1 (10–15%)." (PMID 39658088, 2025). "Loss-of-function mutations in NF1 occur in nearly 20% of melanomas, manifesting as missense or truncating mutations, as well as chromosomal deletions." (PMID 40872623, 2025). "Recently, neurofibromatosis type 1 (NF1) mutations have been reported in patients with malignant melanoma (MM)." (PMID 41001300, 2025). "Because the loss of NF1 in the human melanoma cases was heterozygous, we generated Nf1 haploinsufficiency in the mice." (PMID 39804140, 2025). "The loss of one copy of Nf1 accelerated the formation and/or growth of intradermal melanomas, as these tumors were detected earlier in the Nf1flox/+ mice." (PMID 39804140, 2025). "It should also be noted that somatic mutations in NF1 are frequent in a rare type of melanoma known as desmoplastic melanoma." (PMID 39804140, 2025). "NF1 mutations are a defining feature of DM and are also seen in other melanomas associated with chronic sun exposure." (PMID 40984902, 2025). "As dedifferentiated melanomas frequently occur on highly sun-damaged skin, NF1 mutations are the most commonly encountered." (PMID 40506928, 2025). "Conversely, NRAS-mutant and NF1-mutant melanomas are more aggressive and linked to poorer prognosis, while triple wild-type cases generally respond less favorably to immunotherapy." (PMID 41465101, 2025). "This is consistent with published data showing that preclinically the combination of type II RAF inhibitors and MEK inhibitors is synergistic in colorectal, melanoma, and lung tumor cell lines with mutations in NF1, BRAF, or KRAS." (PMID 40111124, 2025). "NF1 mutations, seen in ~15% of melanomas—mostly in older individuals with high mutational burden—frequently result in loss of function, promoting MAPK hyperactivation." (PMID 41465101, 2025). "High-CSD melanomas often demonstrate RAS-mutated or NF1-mutated profiles in this classification system." (PMID 40125165, 2025). "In this study, we investigated a possible cooperative role of NF1 loss in the context of GNAQ-mutant melanoma." (PMID 39804140, 2025). "NF1 mutations are frequent in melanoma and have been associated with resistance to directed therapies." (PMID 39658088, 2025). "Loss-of-function mutations or deletions in NF1 are associated with reduced responsiveness to BRAF inhibitors in BRAF-mutated melanomas." (PMID 38534309, 2024). "Given the common occurrence of NF1 mutation in BRAF-WT melanoma, which renders patients unsuitable for BRAF targeting, it is crucial to thoroughly understand NF1-mutated melanoma to guide the development of appropriate treatments for this aggressive subtype." (PMID 38534309, 2024). "Currently, the conventional treatment for melanoma patients with NF1 mutations is the use of immune checkpoint therapies." (PMID 38534309, 2024).
melanoma (continued). "In fact, NF1 loss-of-function mutations frequently co-occur with BRAF non-V600 class II mutations; in fact, melanomas harboring BRAF III non-V600 mutations have frequently co-occurring NF1 loss-of-function mutations (67%) and RAS mutations (22%)." (PMID 39727691, 2024). "Markers identified in other NCDTs, such as melanoma and schwannomas, provide valuable insights into CSCs in NF1-associated tumors." (PMID 39518076, 2024). "Compared to over 90% of BRAF, RAS, and NF1 subtypes, only 30% of triple WT melanomas are caused by UV." (PMID 39126091, 2024). "Individuals with NF1 mutations face an elevated risk of developing desmoplastic melanoma, which accounts for 10–15% of melanomas." (PMID 38891988, 2024). "An NF1 mutation is associated with desmoplastic melanomas, while an NRAS mutation is associated with nevoid melanomas." (PMID 38247727, 2024). "NRAS-mutated melanomas and NF1-mutated melanomas are both UV-driven but they are different phenotypically and biologically." (PMID 38247727, 2024). "NF1-mutated melanomas typically arise on chronically sun-exposed skin or in older individuals, exhibit a high mutation burden, and lack BRAF or NRAS mutations." (PMID 38891988, 2024). "Despite the high mutation burden, identification of other actionable mutations in NF1 + melanomas is challenging." (PMID 39340537, 2024). "Because of the shared high-UV signature, NF1 mutation is also frequently seen in high-CSD melanomas of pathway." (PMID 38247727, 2024). "The NF1 loss-of-function mutation is found in 45–95% of desmoplastic melanomas (DMs), which is a subtype of melanoma with severe background solar elastosis." (PMID 38247727, 2024). "Approximately 12–18% of melanoma patients have mutations in NF1, which are most common in elderly and sun-exposed individuals." (PMID 38732242, 2024). "NF1-mutated melanoma is associated with the increased expression of CDC20 and MKI67, which play a crucial role in cell cycle progression, as well as LY6E, which is known to increase the production of proangiogenic agents, including VEGF-A." (PMID 38534309, 2024). "Overall, due to the high CSD and the association with a strong UV signature, NF1-mutated melanomas are found to harbor a greater mutational burden." (PMID 38247727, 2024). "The BRAF mutant is the most common mutant type of melanoma, accounting for over 60% of all cases, and NRAS and NF1 have also been found as common mutation sites in melanoma." (PMID 39659781, 2024). "The high mutational burden in NF1-mutated melanomas demonstrates a favorable outcome for immune checkpoint inhibitor therapy." (PMID 38247727, 2024). "We next examined the functional role of PEDF directly, particularly in the context of melanoma wherein NF1 mutations are associated with more invasive disease in both BRAF mutant and wild type disease." (PMID 39355740, 2024). "We first screened melanoma cell lines for known NF1 mutations, which we confirmed by qRT‐PCR and Western blot analysis." (PMID 39355740, 2024). "Intrinsic resistance to MAPK pathway inhibitor in cell lines with loss of NF1 expression has also been seen in melanoma and glioblastoma, suggesting that there are additional biomarkers of MEK inhibitor sensitivity that require elucidation." (PMID 39001383, 2024). "The third molecular subtype of melanoma is the NF1 + subtype, which is characterized by a deactivating mutation in the NF1 gene." (PMID 39340537, 2024). "The NF1 mutation is more common in fast-growing melanomas with increased Breslow thickness and ulceration." (PMID 39340537, 2024). "Though NF1 mutations are typically seen in melanomas that lack mutations in BRAF or NRAS, nearly 4% of melanomas with mutations in BRAF or NRAS also harbor NF1 mutations." (PMID 38247727, 2024). "KIT mutation (19.1–23.1%) was the most frequently found driver mutation in mucosal melanomas followed by NF1 (7.8–16.4%), RAS (6.2–17.9%), and BRAF (3.1–16.4%) mutations." (PMID 37239381, 2023).